LINC02899 (long independently transcribed non-coding RNA 2899)
Synonyms: FLJ34836; C5orf17
Gene: Long non-coding RNA gene on chromosome 5 (23,951,348 to 24,178,273, forward strand). Ensembl gene ENSG00000248874.
Diseases named in the same sentence as LINC02899 in open-access papers:
LINC02899 is named in the same sentence as 1 disease in open-access papers, as found by Europe PMC text mining. Sharing a sentence is not in itself a finding about the gene and the disease.
LINC02899 shares sentences with these, for which no sentence is quoted: asthma (1 paper).